PMS2P3 (PMS1 homolog 2, mismatch repair system component pseudogene 3)
Synonyms: PMS5; PMSR3; formerly PMS2L9; PMS2L3
Gene: Transcribed unprocessed pseudogene on chromosome 7 (75,510,931 to 75,516,235, reverse strand). Ensembl gene ENSG00000127957.
Diseases named in the same sentence as PMS2P3 in open-access papers:
PMS2P3 is named in the same sentence as 3 diseases in open-access papers, as found by Europe PMC text mining. Sharing a sentence is not in itself a finding about the gene and the disease. The quoted sentences say what the papers report.
colorectal cancer (1 paper, 2022). A primary or metastatic malignant neoplasm that affects the colon or rectum. "Noticeably, PMS2P3 gene belongs to the mismatch repair (MMR) system, which has been observed to have a stronger effect among smokers in affecting colorectal cancer risk, relative to the never smokers." (PMID 36303815, 2022).
PMS2P3 also shares sentences with these, for which no sentence is quoted: breast carcinoma (1 paper); Fanconi anemia (1).